TREM1 (triggering receptor expressed on myeloid cells 1)
Diseases named in the same sentence as TREM1 in open-access papers (continued):
Sharing a sentence is not in itself a finding about the gene and the disease.
Obesity (continued). "The same can be speculated for the TREM-1 pathway, however, no study has investigated how TREM1 affects adipose tissue in the condition of obesity." (PMID 32906847, 2020). "Since the appropriate inflammatory biomarkers in obesity are not well defined, we selected and examined an array of diverse biomarkers (IL6, IL8, PCT, TREM-1, and uPAR), of different cellular sources and pathophysiological roles to cover diverse etiology-based types of inflammations." (PMID 40003433, 2025).
psoriasis (13 papers, 2010 to 2025). An autoimmune condition characterized by red, well-delineated plaques with silvery scales that are usually on the extensor surfaces and scalp. "To confirm the results obtained by RNA‐seq, we performed qPCR to detect and quantify CXCL1, CXCL2, CXCL8, CSFR3, OSM and TREM1, in addition to the psoriasis‐associated genes IL‐17A and IL‐23." (PMID 40181552, 2025). "TREM1 is found co‐expressed on neutrophils and has been found to be involved in the early phase of psoriasis." (PMID 40181552, 2025). "Certain other inflammatory disorders such as pancreatitis, gastric ulcers, psoriasis, ulcerative colitis, and vasculitis situations when TREM1 may be over-expressed." (PMID 39149674, 2024). "Moreover, an earlier study in a psoriasis model showed that TREM-1 blockade in vitro and ex vivo significantly reduced the number of Th17 cells and decreased the secretion of IL-17, suggesting that TREM-1 positively regulates Th17 responses." (PMID 31581596, 2019). "The differential expression analysis identified several upregulated differentially expressed genes, including OSM, CXCL8, TREM1, CXCL1, CSF3R, BCL2A1 and CXCL2, in relapsed psoriasis skin compared with baseline lesional skin." (PMID 40181552, 2025). "In a psoriasis model, Triggering receptor expressed on myeloid cells 1 (TREM‐1) blockade significantly reduced the number of Th17 cells and subsequently decreased IL‐17 secretion, indicating that TREM‐1 positively regulates Th17 responses." (PMID 39264247, 2024). "However, TREM-1 expression is almost undetectable in noninfectious inflammation, such as psoriasis, ulcerative colitis, and vasculitis, despite the increased neutrophil levels." (PMID 29854781, 2018).
septic shock (13 papers, 2011 to 2026). Shock caused by infection; frequently caused by gram negative bacteria, although some cases have been caused by other bacteria, viruses, fungi, and protozoa; characterized by fever, chills, tachycardia, tachypnea, and hypotension. "TREM-1 is highly activated on the cell membranes of blood neutrophils and monocytes and of endothelial cells of patients with septic shock." (PMID 40007937, 2025). "Additionally, after LPS-induced septic shock, TREM-1-/- mice had decreased neutrophil extracellular trap (NET) release in the serum and lungs, which have pro-inflammatory functions that contribute to the progression of septic shock." (PMID 35784361, 2022). "In addition, the expression level of TREM-1 mRNA in neonates with septic shock was significantly lower than that in EOS and LOS, and the difference was statistically significant." (PMID 35935355, 2022). "Patients admitted to the ICU with septic shock have higher surface expression of TREM-1 on monocytes and elevated circulating levels of the cleaved soluble extracellular portion of TREM-1 (sTREM-1)." (PMID 35784361, 2022). "As we known, TREM-1 could amplify the inflammatory response and inhibition of TREM-1 could decrease death in various experimental septic shock models." (PMID 27244892, 2016). "This study examined the role of serum sTREM-1 and TREM-1 expression on cellular surfaces, offering a comprehensive analysis of the inflammatory landscape following abdominal surgery across noninfected, septic, and septic shock patient groups." (PMID 41273150, 2026). "We recently showed that the pharmacological inhibition of TREM-1 (with the synthetic peptide LR12) or the genetic ablation of TREM-1 in endothelial cells reduced neutrophil infiltration, vascular endothelial dysfunction, and death in various experimental septic shock models." (PMID 33420354, 2021). "Flow cytometric data revealed that septic shock patients had significantly lower percentages of TREM-1 expressing classical monocytes, neutrophils and NK-cells, and increased TREM-1 positive nonclassical monocytes." (PMID 41425588, 2025).
influenza (12 papers, 2015 to 2023). An acute viral infection of the respiratory tract, occurring in isolated cases, in epidemics, or in pandemics; it is caused by serologically different strains of viruses (influenzaviruses) designated A, B, and C, has a 3-day incubation period, and usually lasts for 3 to 10 days. "Enriched canonical pathways included activation of the cytokine/chemokine responses to influenza, pathogen-induced cytokine storm signaling, and TREM1 signaling." (PMID 38132091, 2023). "The transcriptional changes in M2-like macrophages highlighted several interesting pathways downregulated when comparing KO to WT, including Hypercytokinemia in the Pathogenesis of Influenza, Role of Pattern Recognition Receptors, and TREM1 Signaling." (PMID 36821386, 2023). "recently showed that TREM-1 knockout protects against severe influenza infection, although viral clearance was unaltered in knockout animals." (PMID 34887856, 2021). "We used a study of anti-TREM1 effects on influenza response, as an example." (PMID 31355053, 2019). "In contrast, TREM1 and TLR pathways were activated in all five infections, whereas upregulation of IFN signaling pathways was predicted in only Lyme disease and influenza." (PMID 26873097, 2016). "Interestingly, we observed increased levels in TREM-1 only during the 1st wave, suggesting a wave-dependent differential migration in H1N1 patients; therefore, we propose that the expression of both CD62L and TREM-1 could be useful in the study of waves in influenza infection." (PMID 26696552, 2015).
malaria (12 papers, 2009 to 2025). Malaria is a serious and sometimes fatal disease caused by a parasite that commonly infects a certain type of mosquito which feeds on humans. "Another gene in this list of 105 highly variable genes is TREM1, which encodes triggering receptor expressed on myeloid cells 1 and is an ancestral predictor for malaria susceptibility." (PMID 41332587, 2025). "Higher soluble form of TREM-1 levels were observed among children in Ghana suffering from severe malaria compared with those of uncomplicated malaria, indicating that high plasma levels of TREM-1 were associated with the development of severe malaria." (PMID 34899708, 2021). "The increase in serum levels of the soluble form of TREM-1 (sTREM-1) has been associated with more severe profiles in other parasitic diseases, such as visceral leishmaniasis, and has also been reported in malaria by P. falciparum." (PMID 35749690, 2022). "Moreover, studies have demonstrated the impact of polymorphisms in the TREM-1 gene on the susceptibility, inflammatory role and prognosis of malaria and other diseases." (PMID 35749690, 2022). "TREM-1 has been implicated as a biomarker of macrophage activation in human malaria patients." (PMID 34899708, 2021). "Our data indicate that Kupffer cells/macrophages are the predominant source of Gal-9, Tim-3, IFNα, IFNβ, IFNγ, and TREM-1, and play an important role in the liver damage during the erythrocytic stage of malaria induced by PbANKA infection." (PMID 34899708, 2021). "We identified novel host biomarkers of pediatric severe and fatal malaria (soluble TREM-1 and soluble Flt-1) and generated simple biomarker combinations that accurately predicted death in an African pediatric population." (PMID 21364762, 2011). "In the present study, the diagnostic accuracy of plasma soluble Triggering Receptor Expressed on Myeloid cells 1 (TREM-1), neopterin and procalcitonin was evaluated as potential markers for malaria disease severity in travellers with imported malaria." (PMID 20840738, 2010). "Surprisingly, 98.4% of total blood MO of the healthy malaria-exposed individuals were TREM-1 positive, indicating that MO from these individuals were activated." (PMID 19851453, 2009). "Patients' MO had significantly lower percentages of CD56 and mIFN-γ and higher percentages of CCR2+CX3CR1+ than malaria-exposed individuals, and high expression of the inflammatory marker TREM-1." (PMID 19851453, 2009). "However, the mechanism of how the IFN-I and TREM-1 influence liver injury during the erythrocytic stage of malaria required further investigation." (PMID 34899708, 2021). "Together, these findings raise the possibility that TREM-1 may contribute to the excessive inflammation characteristic of severe malaria." (PMID 21364762, 2011). "Interestingly, a recent report demonstrated increased levels of monocyte TREM-1 in uncomplicated malaria cases compared to uninfected individuals." (PMID 21364762, 2011). "Moreover, MO from patients showed a significantly increased expression levels of TREM-1, a marker of inflammatory MO, compared to the healthy malaria-exposed controls." (PMID 19851453, 2009). "In our study MO from malaria-exposed individuals showed markedly increased expression of CD56, mIFN-γ and mTNF-α, TREM-1 and HLA-DR, in the classical MO subset." (PMID 19851453, 2009). "In the present study, the diagnostic accuracy of plasma soluble Triggering Receptor Expressed on Myeloid cells 1 (TREM-1), neopterin and procalcitonin levels as biomarkers for severe Plasmodium falciparum disease was evaluated in 104 travellers with imported malaria (26 patients with non-P." (PMID 20840738, 2010). "TREM-1 is able to enhance the secretion of pro-inflammatory cytokines during acute inflammation and/or bacterial or fungal infection, but its involvement in human malaria has not been determined." (PMID 19851453, 2009).
malaria (continued). "In these 13 children, CRP, s-TREM-1, CD163 and HMGB1 were higher than in those negative for malaria parasites, but these differences were not significant." (PMID 19675669, 2009).
breast carcinoma (11 papers, 2015 to 2025). "In this study, authors demonstrated that low TREM-1 levels were significantly associated with favorable response in patients with FID breast cancer (p = 0.05)." (PMID 35875168, 2022). "Higher TREM1 expression was robustly associated with worse distant metastasis-free survival in both ER-negative (basal-like) and ER-positive (Luminal A/B) breast cancers." (PMID 34956864, 2021). "CCL2 has been implicated in promoting breast cancer metastasis as well as prostate cancer growth while TREM1 expression in hepatic satellite cells negatively correlated with disease outcome and its expression was related to aggressive tumor behavior." (PMID 26573568, 2015). "We also observed evidence that TREM1’s inferior outcome association in breast cancer may depend, in part, on an otherwise favorable immunological context." (PMID 34956864, 2021). "First, our interpretations regarding the role of TREM-1 in breast cancer are based solely on correlative analyses, statistical associations and inferences drawn from other cancer research." (PMID 34956864, 2021). "Third, how other pathological processes and pathways operative in breast cancer correlate with TREM-1 expression, the immune subclasses, or clinical endpoints cannot be comprehensively determined from this study." (PMID 34956864, 2021). "In contrast to the breast cancer model, there was little TREM-1 expression on the F4/80- population in RENCA tumors." (PMID 35223446, 2021). "Further study of the role of TREM-1 inhibition in breast cancer as a tool to overcome resistance to immune checkpoint blockade is warranted." (PMID 34956864, 2021). "TREM1 is differentially up-regulated in all breast cancer subtypes, especially in Basal-like (BL) breast cancers, and HER2-positive (HER+) breast cancers." (PMID 33664852, 2021). "Together, these findings suggest that TREM-1 signaling is frequently operative in breast cancer, and that myeloid cells are the predominant source of TREM-1 signaling in the TME." (PMID 34956864, 2021). "Using the 4T1 breast cancer model, we found TREM-1 and TREM-2 expression on MDSC and TAM and that sTREM-1 was elevated in tumor-bearing mice in multiple models and correlated with tumor volume." (PMID 35223446, 2021). "Recently, TREM-1 expression was also first studied in a large series of 701 human breast cancers samples (obtained before neoadjuvant chemotherapy), classified in three distinct immune groups (favorable/weak or poor immune dispositions (FID/WID or PID) respectively; based on immune gene signatures)." (PMID 35875168, 2022). "Interestingly, TREM1 is aberrantly overexpressed in breast cancer tissue as compared to adjacent normal tissue, based on the expression profiles of breast cancer cohort from The Cancer Genome Atlas (TCGA)." (PMID 33664852, 2021). "Together, these findings indicate that increased TREM1 expression is prognostic of inferior breast cancer outcomes and may contribute to myeloid-mediated breast cancer progression and immune suppression." (PMID 34956864, 2021). "Indeed, TREM1 expression was stronger in breast cancer tissue compared to normal tissue." (PMID 33664852, 2021). "Moreover, we observed that myeloid TREM1 frequency also associated with clinical breast cancer subtype (TNBC, ER+, HER2+), whereby an overall difference in rank of the percentage of TREM1-expressing cells was significant (P=0.03, three-group Kruskal-Wallis test)." (PMID 34956864, 2021). "In tumor tissue sections from breast cancer (BRCA), LC, and KIRC, regions containing TREM1+ PMN-MDSCs exhibited significantly enhanced immunosuppressive activity, suggesting a role for TREM1+ PMN-MDSCs in promoting immunosuppression within the TME." (PMID 41413734, 2025). "We detected significantly elevated TREM1 protein within the TME of LIHC, GBM, breast cancer, and melanoma." (PMID 37651197, 2023).
breast carcinoma (continued). "This is the first demonstration that TREM1 expression in human breast cancers has negative prognostic and therapeutic implications for breast cancer patients." (PMID 35875168, 2022). "To further confirm the TREM1 expression pattern in breast cancers, we performed IHC analysis for TREM1 in breast cancer and non-tumor tissue samples." (PMID 33664852, 2021). "By univariate Cox regression analysis, TREM1 was associated with DMFS in both estrogen receptor positive (ER+) and negative (ER-) breast cancers, as well as lymph node positive (LN+) and negative (LN-) disease." (PMID 34956864, 2021). "The role of the soluble protein TREM1 as possible prognostic marker to detect lung metastasis was previously reported; nevertheless no study has investigated the role of TREM1 in the peripheral blood of breast cancer patients." (PMID 26884644, 2016). "Based on these data, we hypothesize that ASS1 expression restores arginine metabolism in M231-ADIR cells, whereas TREM1 expression stimulates AKT/mTOR/STAT3 and a CCL2 feed-forward loop to provide survival signals contributing to ADI resistance in breast cancer cells." (PMID 33664852, 2021). "Similar TREM1 expression patterns were observed among cell types grouped by tumor subtype (TNBC, n=13; ER+, n=15; HER2+ (ER+/-), n=3), and within tumors of individual patients, confirming that TREM1 expression in breast cancer is a predominantly myeloid phenomenon." (PMID 34956864, 2021).
depression (11 papers, 2019 to 2025). "Herein on the contrary, downregulation of both LRG1 and TREM1 was associated with depression only during pregnancy, in line with a possible pregnancy-only related signature." (PMID 40473930, 2025). "For example, quercetin attenuates LPS-induced depression-like behavior and learning memory impairment in rats, which may be related to its modulation in the imbalance of hippocampal Copine 6 and TREM1/2 expression associated with brain-derived neurotrophic factor." (PMID 35369029, 2022). "This prospective observational study aims to investigate the impact of JWZX granules on serum TREM1 expression and its regulatory role in depression and anxiety in patients with CHD." (PMID 40922326, 2025). "In this study, we investigated the effects of JWZX granules on serum TREM1 levels and their regulatory role in depression and anxiety in CHD patients." (PMID 40922326, 2025). "This study explored the effects of Jiuwei Zhenxin (JWZX) granules on serum triggering receptor expressed on myeloid cells 1 (TREM1) levels and their role in regulating depression and anxiety in patients with coronary heart disease (CHD)." (PMID 40922326, 2025). "Apart from an imbalanced protein expression of TREM1 and TREM2 in the hippocampus of depression or AD rat model, results of our previous study have shown a turbulence of TREM1 and TREM2 abundance in T2DM patients." (PMID 36619542, 2022). "In the present study, the LPS-challenged rats presented not only depression-like behaviors and impairment of learning and memory, but also the decreased expression of TREM1 and increased expression of TREM2 in the hippocampus and PFC." (PMID 32009956, 2019). "Furthermore, TREM-1 deficiency had no impact on motor function or emotion-related behaviors, including depression-like behavior." (PMID 39809747, 2025). "Our research demonstrated that JWZX treatment significantly reduced depression and anxiety in CHD patients and modulates serum TREM1 levels." (PMID 40922326, 2025). "Quercetin alleviates LPS-induced depression-like behavior and learning and memory impairment in rats by regulating BDNF-related imbalance of Copine 6 and TREM1/2 expression in the hippocampus." (PMID 34257681, 2021). "Quercetin alleviates LPS-induced depression-like behavior in rats by regulating BDNF-related imbalance of copine 6 and TREM1/2 in the hippocampus and PFC." (PMID 35003290, 2021). "The results suggested that quercetin could alleviate LPS-induced depression-like behaviors and impairment of learning and memory in rats, the mechanism of which might be involved with regulating the BDNF-related imbalance expression of Copine 6 and TREM1/2 in the hippocampus and the PFC." (PMID 32009956, 2019).
diabetes (10 papers, 2019 to 2025). "A recent study on TREM1 (triggering receptor expressed on myeloid cells 1), a receptor of the immunoglobulin superfamily expressed on myeloid cells, indicated a relationship between chronic periodontal illness and type 2 diabetes mellitus." (PMID 40028480, 2025). "Thus, the Diabetes + Infected group showed significant activation of the TREM-1 signaling pathway compared with the Ctrl + Infected group, likely exacerbating the infection." (PMID 38098038, 2023). "Interestingly, our study showed TREM1 was positively associated with HbAC and FPG; and TREM1 expression was significantly increased in patients with both AMI and diabetes compared to those with only AMI." (PMID 34221733, 2021). "TREM1 is a potentially significant biomarker for the diagnosis of AMI and may be closely associated with the severity of coronary lesions and diabetes." (PMID 34221733, 2021). "TREM1 expression showed a significant difference in the normal and AMI groups in diabetes subgroups." (PMID 34221733, 2021). "Compared to the normal group without diabetes, TREM1 expression was higher in the AMI group with or without diabetes (p < 0.05)." (PMID 34221733, 2021).
acute kidney injury (9 papers, 2015 to 2025). Sudden and sustained deterioration of the kidney function characterized by decreased glomerular filtration rate, increased serum creatinine or oliguria. "The canonical pathways including acute phase response-, EIF2-, TREM1-, IL-6-, HMBG1-, PPAR signaling, and LXR/RXR activation were associated with acute heart, pulmonary, and renal failure." (PMID 32154187, 2020). "Inhibition of TREM-1 expressed on renal endothelial cells reduces the production of inflammatory cytokines and angiogenic factors after stimulation with DAMPs, potentially attenuating acute kidney injury." (PMID 37168858, 2023).